IL6 (interleukin 6)
Diseases named in the same sentence as IL6 in open-access papers (continued):
Sharing a sentence is not in itself a finding about the gene and the disease.
genital herpes (2 papers, 2010 to 2025). Herpes simplex infection of the genitals, most commonly caused by the herpes simplex-2 virus. "PBMC from HSV-2 meningitis patients secreted higher levels of several Th1 (IFN-γ) and inflammatory cytokines (IL-6, LIF, IL-8) in response to HSV-2 compared to PBMC from HSV-2 genital herpes patients." (PMID 40534882, 2025). "IRIS cases with bacterial scalp abscess or genital herpes had decreased IL-6 compared to their non-IRIS controls." (PMID 20929543, 2010).
Gilbert syndrome (2 papers, 2021 to 2022). An autosomal recessive inherited disorder characterized by unconjugated hyperbilirubinemia, resulting in harmless intermittent jaundice. "Our findings are consistent with previous observations in patients treated with tocilizumab, another IL-6Rα inhibitor, and suggest that IL-6 pathway inhibition leads to decreased UDP-glucuronosyltransferase 1-1 activity in Gilbert’s syndrome patients." (PMID 35149777, 2022). "One possible explanation for this positive association is that unconjugated bilirubin might affect the immune response by downregulating intracellular production of cytokines, as evident from the decreased IL-6 and IL-1β level in monocytes from individuals with Gilbert's Syndrome." (PMID 34603596, 2021). "Second, the NHANES database does not collect data on unconjugated bilirubin, Gilbert's Syndrome, and cytokines level, such as IL-6 and IL-1β." (PMID 34603596, 2021).
Gorham-Stout disease (2 papers, 2011 to 2020). Gorham-Stout disease (GSD) is a rare disease of massive osteolysis associated with proliferation and dilation of lymphatic vessels. "In reported studies, several factors were measured in the blood of patients with Gorham-Stout disease (e.g., vascular endothelial growth factors, IL-6, sRANKL, and osteoprotegerin)." (PMID 32117063, 2020). "In case reports of Gorham-Stout disease the serum levels of IL-6 are sometimes elevated." (PMID 32117063, 2020). "IL-6 and VEGF-A were elevated in the blood of patients with Gorham-Stout disease, and in a recent study also the levels of pyridinoline cross-linked carboxyterminal telopeptide of type I (ICTP) and sclerostin." (PMID 32117063, 2020).
hand (2 papers, 2014 to 2025). "Previously our group reported the associations of the IL1 and IL6 gene polymorphisms with hand OA." (PMID 25252624, 2014). "In HIV-associated neurocognitive disorders (HAND), p62 phosphorylation under oxidative stress amplifies neuroinflammation through increased expression of cytokines (MCP-1, IL-6, COX-2), driving disease progression." (PMID 40643536, 2025).
hand osteoarthritis (2 papers, 2019 to 2024). "We tested the potential of circulating galectin-1, interleukin (IL)-1 beta, IL-6, and tumour necrosis factor alpha (TNF alpha) levels at baseline in individuals with knee pain as biomarkers for development of radiographic knee and/or hand osteoarthritis (OA)." (PMID 38469554, 2024).
hay fever (2 papers, 2006 to 2019). "A novel finding of our study was the association of a protective heterozygous effect of the IL6(-174C>G) polymorphism with the risk for hay fever and with IgE levels in hay fever cases." (PMID 16759385, 2006). "Subjects with IL6(-174) GG genotype exhibited higher total serum IgE levels than subjects with IL6(-174) GC or CC genotypes if they reported hay fever." (PMID 16759385, 2006). "In the large, well-characterized SAPALDIA cohort the IL6(-174G>C) and IL18(-137G>C) polymorphisms were associated with circulating total IgE concentrations in subjects with hay fever." (PMID 16759385, 2006).
Hema (2 papers, 2020 to 2022). "When the immunological profile of untreated patients with hemophilia A was assessed in comparison with the profile of healthy controls, higher levels of IL-4, IL-6, IL-8, IL-10, IL-12 and IL-17 were detected." (PMID 35186990, 2022). "Increased levels of the pro-inflammatory cytokines IL-1β, IL-6, keratinocyte-derived chemokine (KC) and monocyte chemotactic protein-1 (MCP-1) were also detected in synovial fluid of hemophilia A mice with experimentally induced joint hemorrhage." (PMID 35186990, 2022). "The hmrSCs response to BMP9 was enhanced by both Hema and HH, even though several cytokines were upregulated (IL-6, IL-8, MCP-1, VEGF-A and osteopontin), downregulated (BMP9, PDGF) or similar (TNF-alpha) in Hema compared with HH." (PMID 32325892, 2020).
hemorrhagic cystitis (2 papers, 2019 to 2021). Inflammation of the bladder resulting in bloody urine. "Increasing inflammatory mediators such as TNF-α, IL-6, and IL-1β in hemorrhagic cystitis will further aggravate the inflammatory response." (PMID 34804174, 2021). "Another potential approach to treat chemotherapy-induced hemorrhagic cystitis is to administer IL-412, a potent anti-inflammatory cytokine known to antagonize the IL-1β, TNFα and IL-6 pathways." (PMID 30733505, 2019). "Other candidate drugs for ifosfamide-induced hemorrhagic cystitis have also been shown to specifically target the IL-1β-TNFα-IL-6 pathway." (PMID 30733505, 2019). "Candidate drugs targeting the inflammatory IL-1β, TNFα and IL-6 triad and/or promoting antioxidant responses show promise for ameliorating hemorrhagic cystitis but have not progressed beyond preclinical testing." (PMID 30733505, 2019). "Besides effects on the IL-1β, TNFα and IL-6 triad, IPSE may also mediate critical gene expression changes in chemokines during ifosfamide-induced hemorrhagic cystitis." (PMID 30733505, 2019).
Hepatomegaly (2 papers, 2020 to 2025). Abnormally increased size of the liver. "It is therefore conceivable that the IL-6 itself drives hepatomegaly among POEMS patients with elevated IL-6." (PMID 40646134, 2025).
herpangina (2 papers, 2021 to 2023). "EV71-infected patients with HFMD, herpangina, severe brainstem encephalitis, and other manifestations associated with the central nervous system exhibit different proinflammatory responses, such as increased levels of IL-6, IL-8, and other cytokines." (PMID 37207203, 2023). "EV-A71 infection induced interferon, pro-inflammatory cytokines and chemokines, including IFN-β, IL-6, CCL5, and TNF-α in tonsillar epithelial cells, which may play a critical role in EV-A71-caused herpangina." (PMID 33481814, 2021).
herpes simplex encephalitis (2 papers, 2021 to 2024). Herpes simplex virus encephalitis (HSE) is caused by the infection of the central nervous system by Herpes simplex virus (HSV) that could have a devastating clinical course and a potentially fatal outcome particularly with delay or lack of treatment. "During the ascending phase of herpes simplex encephalitis, the expression of CTRP4 in the brain was closely related to serum levels of IL‐6 and TNF‐α, volumes of brain damage, and the decline in MMSE scores." (PMID 38334009, 2024).
histiocytic lymphoma (2 papers, 2022 to 2023). "Oncostatin-M (OSM) is an interleukin-6 (IL-6) family cytokine first isolated in 1986 from human histiocytic lymphoma U937 cells." (PMID 37841259, 2023).
human papillomavirus infection (2 papers, 2021 to 2022). "Similarly, activation of the transcription factor NF-κB, involving the small GTPase Rac1, was required for IL-6 production and subsequent STAT3 activation in human papillomavirus infection, indicating that link between NF-κB and IL-6 might be a common feature of DNA viruses." (PMID 35458402, 2022).
hydrocele (2 papers, 2025). "The presence of inflammatory mediators, such as interleukins (IL-1, IL-6) and tumor necrosis factor-alpha (TNF-α), has been noted in the fluid of hydroceles, suggesting an underlying inflammatory component that can influence hydrocele formation and maintenance." (PMID 40137708, 2025).
hyperamylasemia (2 papers, 2016 to 2025). Abnormally high level of amylase in the blood. "The massive release of neurohormones can also result in hyperamylasemia which is also strongly correlated to interleukin 6 (IL6)." (PMID 41327440, 2025).
Hyperhidrosis (2 papers, 2019 to 2025). Abnormal excessive perspiration (sweating) despite the lack of appropriate stimuli like hot and humid weather. "The PHO-related symptoms including joint swelling and hyperhidrosis, as well as the increased biochemical markers including ALP, β-CTX, hsCRP and IL-6 have also been markedly improved within 6 months." (PMID 31063976, 2019).
hypersensitivity (2 papers, 2021 to 2022). An inflammatory response to an exogenous environmental antigen or an endogenous antigen initiated by the adaptive immune system. "Incidence of hypersensitivity reactions with the use of different IL-6 inhibitors." (PMID 36091800, 2022). "This hypothesis is also sustained by the findings of higher IL-6 levels in patients who received rituximab and developed a hypersensitivity reaction." (PMID 35153748, 2021).
hypersplenism (2 papers, 2021 to 2022). Overactive functioning of the spleen, resulting in excessive destruction of blood cells. "Enhanced breakdown of PLTs due to hypersplenism together with increased release of interleukin-6 shortens PLT life cycle." (PMID 33644233, 2021).
hypopharyngeal carcinoma (2 papers, 2017 to 2022). Carcinoma, predominantly squamous cell, arising from the epithelial cells of the hypopharynx. "Normal fibroblasts are also capable of secretion of IL-6, IL-8 and GROα and the interleukin 6 and 8 release significantly increases in presence of either keratinocytes or cancer cells (FaDu hypopharyngeal carcinoma epithelial cells)." (PMID 29236046, 2017). "We also show that all three STAT3 inhibitors, with STA‐21 having the most profound effect, can effectively suppress the continuous production of cancer‐related molecules, IL6, TNF, RELA(p65), EGFR, BCL2 and STAT3, previously associated with hypopharyngeal cancer, caused by acidic bile." (PMID 34850540, 2022).
hypoxia (2 papers, 2022 to 2025). A decrease in the amount of oxygen in the body. "MLR and IL-6 (associated with inflammatory and peripheral endothelial dysfunction) were high in Vata patients; diabetic control (associated with plaque instability and malfunctioned RAAS) was poor in Kapha patients and NT-pro BNP (associated with myocardial hypoxia) was higher in Pitta patients." (PMID 40829435, 2025).
idiopathic membranous nephropathy (2 papers, 2021 to 2022). "Interleukin 6 and CXCL1 have been suggested to be involved in the progression of renal injury in IgA nephritis, while IL-8 levels were associated with poor prognosis in idiopathic membranous nephropathy." (PMID 33800255, 2021).
idiopathic pneumonia syndrome (2 papers, 2022 to 2023). "This cell-intrinsic IDO1-AHR pathway represses STAT1-mediated IL6 expression and subsequently prevents CD4+ T cells from differentiating into pathogenic Th17 cells, which are a major effector responsible for idiopathic pneumonia syndrome (IPS)." (PMID 37394584, 2023). "Previous reports have revealed that pulmonary-derived IL-6 induces idiopathic pneumonia syndrome through the promotion of Th17 differentiation." (PMID 35140545, 2022).
infectious encephalitis (2 papers, 2022 to 2025). An acute infectious process that affects the brain tissue. "Subgroup analysis results are consistent and show that in both autoimmune and infectious encephalitis, CSF concentration of IL-6 is higher than controls (SMD (autoimmune), 1.90; 95% CI, 0.71–3.90; P < 0.01; SMD (infectious), 1.28; 95% CI, 0.75–1.80; P < 0.01)." (PMID 36048783, 2022). "A non-human primate model of ICANS demonstrated an elevation of CSF cytokines, such as IL-6, IL-2, GM-CSF, and vascular endothelial growth factor (VEGF), together with CAR-T and non-CAR-T-cell accumulation in the CSF and brain parenchyma, similar to that seen in non-infectious encephalitis." (PMID 40332772, 2025).
Inguinal hernia (2 papers, 2022 to 2025). Protrusion of the contents of the abdominal cavity through the inguinal canal. "In patients with inguinal hernia, serum IL-6, CRP, and MMP-9 increase first and then decrease after surgery, reaching the peak value around 24 or 48 h after surgery." (PMID 40292257, 2025). "Serum IL-6, CRP, and MMP-9 levels in patients with inguinal hernia can affect the efficacy of modified preperitoneal Kugel repair and the prognosis of patients." (PMID 40292257, 2025). "This indicates that preoperative serum IL-6 and CRP levels affect the prognosis of patients with inguinal hernia." (PMID 40292257, 2025). "Therefore, serum IL-6, CRP, and MMP-9 in patients with inguinal hernia before surgery will affect the surgical efficacy and prognosis of patients." (PMID 40292257, 2025).
internalizing disorder (2 papers, 2021 to 2022). A type of mental or behavioral disorder, typically in children and young adults, with symptoms including depression, anxiety and withdrawal. "We were also unable to find an association with basal IL-6 levels and pediatric internalizing disorders." (PMID 35880170, 2022). "Evidence has also been gathered on the association between IL-6 level and internalizing disorder symptoms." (PMID 34576215, 2021). "Further study is warranted to determine the mechanism of the mediating role that IL-6 may have in pediatric internalizing disorders." (PMID 35880170, 2022).
intrahepatic cholestasis (2 papers, 2022 to 2025). A cholestasis characterized by impairment of the bile flow caused by obstruction located in the liver. "KEGG enrichment and western blot analyses showed that signaling axes of JNK/IL-6/NF-κB/STAT3 related to PPARα might be the principal pathway DCHT affects intrahepatic cholestasis." (PMID 35370715, 2022).
iritis (2 papers, 2022 to 2024). Inflammation of the iris. "Aqueous humor was analyzed in three selected patients (Case 1 with iritis, Case 3 and Case 4 with VKH-like disease) and revealed significantly elevated IL-6 (range 734.2–2120.4 pg/mL) and mild to moderate elevated IFN-γ (range 27.4–855.0 pg/mL)." (PMID 35335114, 2022).
Kaposi disease (2 papers, 2023 to 2024). "These genes would have been integrated by HHV-8 during its evolution, HHV-8 has a gene that encodes for a protein close to human interleukin 6 (vIL-6), whose role seems to be pivotal in the pathogenesis of Kaposi’s disease." (PMID 37491285, 2023). "Variation of Il-6 concentration and oxidative parameters as a function of the risk of Kaposi’s disease." (PMID 37491285, 2023). "Upon asthmatic immunopathology, plasma levels of MDA were significantly (p < 0.001) enhanced in asthmatics and were significantly related to IL-6, while a weak positive correlation between IL-6 and MDA was found in HIV-infected patients with or at risk of Kaposi’s disease." (PMID 39195804, 2024). "Investigating the relation between Interleukin-6 concentration and oxidative status of HIV-infected patients on ARV treatment with or at risk of Kaposi’s disease, the frequency of the HHV-8 antigen was 57.5% and the prevalence of clinical signs of Kaposi’s disease was 3.4%." (PMID 37491285, 2023). "Our study showed a weak positive correlation between IL-6 and MDA, a strong negative correlation between FRAP and MDA and a strong positive correlation between MDA and GSH highlighting the association of these few markers of oxidative stress and Il-6 to the risk of Kaposi’s disease." (PMID 37491285, 2023).
laminopathies (2 papers, 2021 to 2025). "In this study, we systematically examined various mitochondrial stressors that previously observed in different laminopathies and identified IL‐6‐dependent dysregulation of intracellular Ca2+ levels as a novel factor contributing to mitochondrial dysfunction." (PMID 39661729, 2025). "Here, we confirmed increase of IL6 in the culture medium of HGPS fibroblasts and showed IL6 increase also in Mandibuloacral Dysplasia cells, suggesting that IL6 signaling could play a role in other LMNA‐linked progeroid laminopathies." (PMID 33393189, 2021).
large artery stroke (2 papers, 2025). Stroke caused by the blockage of blood flow in one of the large arteries feeding the brain. "As expected, genetically downregulated IL‐6 signaling was associated with lower odds of large artery stroke (OR, 0.79 [95% CI, 0.74–0.84]) and carotid plaque (OR, 0.88 [95% CI, 0.83–0.94])." (PMID 41182006, 2025).
lateral epicondylitis (2 papers, 2022). inflammation of the lateral epicondyle. "In patients with lateral epicondylitis and shoulder and Achilles tendinopathy, Tendisulfur® supplementation for 60 days led to a drop in VAS, possibly due to the downregulation of NF-κB, TNF-α and IL-6." (PMID 35329992, 2022).
Legionella pneumonia (2 papers, 2016 to 2024). "Indeed, patients with Legionnaires’ disease show increased level of IL-6 and TNFα in their lungs." (PMID 26741365, 2016).
lentivirus infection (2 papers, 2014 to 2020). Virus diseases caused by the Lentivirus genus. "It is of note that empty vector transfected cells also produced increased IL-6 and IL-8 compared to A20 competent cells possibly due to the effect of cell manipulations (e.g., Lentivirus infection) on cell phenotype which were reported in previous studies." (PMID 32218782, 2020).
lipoma (2 papers, 2018 to 2019). A benign, usually painless, well-circumscribed lipomatous tumor composed of adipose tissue. "There are no data for isolated LDSCs but it has been shown that IL6 and TNF are up-regulated in lipoma tissue compared to adipose tissue, which is probably due to the presence of various immune cells within the tissue." (PMID 30987193, 2019).
lymphoid neoplasm (2 papers, 2022). A neoplasm composed of a lymphocytic cell population which is usually malignant (clonal) by molecular genetic and/or immunophenotypic analysis. "While the pathophysiology of IL-6 signaling in several lymphoid neoplasms has been well studied, the roles of IL-6 in MDS remain observational." (PMID 35900794, 2022).
mad (2 papers, 2018 to 2021). "The VZV IL-6 data are strongly supported by an independent investigation of cytokines present in the skin disease called “mad itch” found in animals infected with the closely related PRV, an alpha herpesvirus in the Varicellovirus genus." (PMID 30568636, 2018).
melasma (2 papers, 2024 to 2025). "We consistently observed that AOPT‐LTL treatment significantly reduced mast cell infiltration and the release of pro‐inflammatory cytokines (TNF‐α, IL‐1β, IL‐6) and the expression of key enzymes regulating inflammatory mediators (iNOS, COX‐2) in a guinea pig model of melasma." (PMID 40916844, 2025).
memory (2 papers, 2025). The activities involved in the mental information processing system that receives (registers), modifies, stores, and retrieves informational stimuli. "The elevated IL-6 in CSF has been identified as a key biomarker of neuroinflammation in NPSLE, and its level is directly correlated with learning and memory deficits." (PMID 41161815, 2025).
metabolic (2 papers, 2018 to 2020). "This increase in TG concentration in serum also induced secretion of cytokines, that is, leptin and IL-6, which are known to have an association with impaired glucose metabolism and insulin sensitivity." (PMID 30319558, 2018).
mucinosis (2 papers, 2014 to 2025). "Drug-related mucinosis has been linked to interferon alfa-1, interferon beta-1, interleukin 12/23 inhibitors (ustekinumab), tumor necrosis factor-alfa inhibitors and interleukin 6 inhibitors (tocilizumab)." (PMID 40535966, 2025). "Interleukin-1 and interleukin-6 have also been shown to be elevated in patients with increased dermal mucin production in SLE and DM; however this is nonspecific as interleukins may be raised without evidence of mucinosis." (PMID 25485159, 2014).
mycobacterial infection (2 papers, 2020 to 2022). "In addition, the alarmin S100A8, known to contribute to neutrophil accumulation during chronic mycobacterial infection, stimulates IL-6 to promote Th17 differentiation." (PMID 35821058, 2022). "Among the molecules, chemokines (CCL3, CCL4, CCL5) and cytokines (IL6, IL1B) are known to induce M1 macrophage polarization in response to mycobacterial infection." (PMID 35821058, 2022).